FOXM1 (forkhead box M1)
Diseases named in the same sentence as FOXM1 in open-access papers (continued):
Sharing a sentence is not in itself a finding about the gene and the disease.
pneumonia (continued). "In summary, our study for the first time demonstrated the protective role of FBXL19 in Spn-induced pneumonia immature mice via ubiquitination and degradation of FOXM1, which provides a theoretical reference for the clinical study of FBXL19 in pediatric pneumonia." (PMID 36964598, 2023). "We first determined that the relative mRNA expression of FOXM1 in the pneumonia group was up-regulated relative to the healthy control group, and the relative protein expression of FOXM1 in the LPS group was also up-regulated relative to that in the control group (all P < 0.01)." (PMID 34301223, 2021). "Taken together, we concluded that si-KCNQ1OT1 might serve as a competitive endogenous RNA to regulate the expression of FOXM1 by sponging miR-370-3p, thereby alleviating injury from pneumonia." (PMID 34301223, 2021). "However, it is unclear whether FBXL19 mediates FOXM1 ubiquitination and further plays a role in Spn-induced pneumonia." (PMID 36964598, 2023). "In addition, the change of FOXM1 mRNA level in the lung and FOXM1 downstream mechanism in Spn-induced pneumonia remain unknown." (PMID 36964598, 2023). "In light of the currently available literatures, we speculated that FBXL19 plays a regulatory role in lung injury in Spn-induced pneumonia immature mice via FOXM1, and aimed to confirm the role and downstream mechanism of FBXL19 in Spn-induced pneumonia immature mice in this study." (PMID 36964598, 2023). "Herein, we uncovered FBXL19 and FOXM1 as regulators of lung injury in Spn-induced pneumonia immature mice and validated a mechanism wherein FBXL19 bound to FOXM1 and induced the ubiquitination and degradation of FOXM1, thus attenuating lung injury in Spn-induced pneumonia immature mice." (PMID 36964598, 2023). "However, our study only confirmed a single molecular mechanism of FBXL19 in Spn-induced pneumonia immature mice, lacking exploration of the mechanism of FBXL19 and FOXM1 downregulation." (PMID 36964598, 2023).
psoriasis (7 papers, 2015 to 2024). An autoimmune condition characterized by red, well-delineated plaques with silvery scales that are usually on the extensor surfaces and scalp. "MiR-214-3p downregulation contributes to psoriasis pathology by causing increased expression of the transcription factor FOXM1; FOXM1 increases cell proliferation by controlling cell cycle dynamics." (PMID 39337637, 2024). "FOXM1 contributes to psoriasis by regulating TNF-α-induced cell proliferation, apoptosis, and inflammation in keratinocytes." (PMID 37238726, 2023). "FOXM1 is a novel tumor biomarker that is involved in modulating psoriasis, keloid, and many other skin diseases." (PMID 36118675, 2022). "To design a candidate cdODN for psoriasis treatment, we focused on a limited set of TFs (FOXM1, IRF1 and NF-κB) as well as the IFN-stimulated gene factor 3 (ISGF3) complex (i.e., STAT1, STAT2 and IRF9)." (PMID 25883770, 2015). "To illustrate this idea, we designed a cdODN to concomitantly target psoriasis-activated TFs (i.e., FOXM1, ISGF3, IRF1 and NF-kappaB)." (PMID 25883770, 2015). "We show that PREs can be strategically combined to create a cdODN concomitantly targeting psoriasis-activated TFs (FOXM1, ISGF3, IRF1 and NF-κB), illustrating how transcriptome informatics can be directly connected to dODN development." (PMID 25883770, 2015). "FOXM1 is one of the core transcription factor regulators in psoriasis." (PMID 32785106, 2020). "Although 106 TFs are encoded by psoriasis DEGs, only a fraction interacts with PREs (26/106), and several of these have not yet been examined in psoriasis studies (e.g., FOXM1, EHF, SOX5)." (PMID 25883770, 2015). "We found that psoriasis and AD share many DEGs and pathways, but also identified regulators, such as FOXE1, FOXM1, STAT3 and SOX7, and discovered a gene regulatory network unique for psoriasis." (PMID 35874668, 2022). "This highlighted SNP-PRE pairs involving PREs recognized by TFs or uDBPs with increased expression in psoriasis lesions (i.e., AVEN, RBM8A and FOXM1)." (PMID 25883770, 2015). "Notably, two additional forkhead box family members (FOXM1 and FOXP3) are also ranked within the top 30 regulators in psoriasis." (PMID 35874668, 2022). "Through in silico screening of known DNA binding sites, our findings highlight proteins not yet well studied in psoriasis, including TFs (FOXM1, EHF, SOX5) and uDBPs (AVEN, RBM8A, GPAM, WISP2)." (PMID 25883770, 2015). "Although cdODN199 includes FOXM1, ISGF3, IRF1 and NF-κB recognition sites, it does not include a binding site for STAT3, previously validated as an effective dODN target in a psoriasis mouse model." (PMID 25883770, 2015). "Additionally, however, we uncovered TFs not extensively studied in psoriasis, but which may nonetheless have important roles in KC differentiation, KC proliferation, apoptosis, inflammation, WNT signaling and lipid synthesis (e.g., FOXM1 and EHF)." (PMID 25883770, 2015).
chronic myeloid leukemia (6 papers, 2012 to 2024). "In K562 cells, an established model of the human chronic myeloid leukemia (CML), quercetin-induced apoptosis has been associated to a reduction of HSP70, Bcl-xL, and FOXM1 transcripts." (PMID 31861640, 2019). "To further investigate this issue, we evaluated FoxM1 expression in a chronic myeloid leukemia K562 cell line and in the related resistant cell line, K562-R." (PMID 23110199, 2012). "However, the elucidation of the signaling pathways involved in FoxM1 expression in chronic myeloid leukemia might be useful to elucidate new strategies for treatment, drug resistance, prognosis and disease progression." (PMID 23110199, 2012). "FOXM1 tyrosine phosphorylation has also been reported in K562 cells (unpublished data), a BCR-ABL-positive human chronic myeloid leukemia cell line." (PMID 39060421, 2024). "A recent study identified FOXM1 as a new STAT3 gene target and clarified its role in proliferation, survival, drug resistance, and DNA repair in chronic myeloid leukemia." (PMID 30782607, 2019). "Our study provides the identification of FoxM1 as a new STAT3 gene target and clarifies its role in proliferation, survival, drug resistance and DNA repair in chronic myeloid leukemia." (PMID 23110199, 2012). "Abnormal expression of Forkhead box protein M1 (FOXM1) and serine/threonine kinase Budding uninhibited by benzimidazoles 1 (BUB1B) contributes to the development and progression of several cancers, including chronic myelogenous leukemia (CML)." (PMID 35847923, 2022). "Additionally, we evaluated the FoxM1 expression profile in a chemoresistant-derived K562/R cell line, which exhibits chemoresistance to imatinib, the most common drug used to treat chronic myeloid leukemia (CML)." (PMID 23110199, 2012).
colon adenocarcinoma (6 papers, 2017 to 2023). "In addition, Moonlight predicted FOXM1 as an oncogene with associated amplification in colon adenocarcinoma and lung squamous cell carcinoma." (PMID 31900418, 2020). "In colon adenocarcinomas, stem cells have been reported to use mitochondrial OXPHOS to produce ATP and maintain mitochondrial function via the FOXM1/PRDX3 pathway, thereby maintaining their survival and stem-cell characteristics." (PMID 36844874, 2023).
cutaneous melanoma (6 papers, 2015 to 2025). A primary melanoma arising from atypical melanocytes in the skin. "In skin melanoma cell lines, MAPK activation was associated with upregulation of AKA mediated by promoter activation with FOXM1." (PMID 35326726, 2022). "The forkhead box protein M1 (FOXM1) is another pivotal factor in cell proliferation and DNA repair, with its overexpression being strongly associated with tumour progression in multiple cancers, including cutaneous melanoma." (PMID 39823244, 2025). "Previous studies have proposed that FOXM1 is up-regulated in cutaneous melanoma." (PMID 38342795, 2024). "Additionally, FOXM1 was verified to be related to cutaneous melanoma growth and may serve as a new therapeutic target for cutaneous melanoma." (PMID 38342795, 2024).
gallbladder cancer (6 papers, 2016 to 2023). "Long non-coding RNA H19 regulates FOXM1 expression through competitively binding to endogenous miR-342-3p in gallbladder cancer." (PMID 37059588, 2023). "It was reported that FoxM1 was highly expressed in gallbladder carcinoma, and its overexpression encouraged multiple carcinomas and predicted a frustrating prognosis." (PMID 36301031, 2022).
Glucose intolerance (6 papers, 2012 to 2023). Glucose intolerance (GI) can be defined as dysglycemia that comprises both prediabetes and diabetes. "It is well known that wild-type male and female mice show differences in glucose tolerance, and some recent studies have reported that male mice are more susceptible to developing glucose intolerance following Cre-loxP-mediated inactivation of critical β-cell genes such as FoxM1 and Ngn3." (PMID 22470452, 2012).
Insulin resistance (6 papers, 2014 to 2025). Increased resistance towards insulin, that is, diminished effectiveness of insulin in reducing blood glucose levels. "A lack of FOXM1 in pancreatic β-cells leads to impaired β-cell adaptive proliferation in mice in response to pregnancy, acute and chronic insulin resistance, or cellular senescence." (PMID 37238726, 2023).
malignant mesothelioma (6 papers, 2012 to 2024). A malignant neoplasm of the pleura or peritoneum, arising from mesothelial cells. "Analysis of human tumor specimens showed FOXM1 is broadly expressed in malignant mesothelioma (MM), an intractable tumor associated with asbestos exposure." (PMID 22761781, 2012). "YAP/TAZ drives the transcription of key cell cycle genes, such as the cell cycle transcription factor forkhead box protein M1 (FOXM1) and its target CCND1 (encoding cyclin D1) in malignant mesothelioma cells." (PMID 38607003, 2024). "FOXM1 is an essential transcription factor in intracellular redox, specifically in regulating the redox state of malignant mesothelioma cells." (PMID 39607749, 2024). "Upregulation of cyclin D1 and Forkhead Box Protein M1 (FOXM1) is required for YAP-driven malignant mesothelioma cell proliferation." (PMID 29642615, 2018). "Moreover, YAP has been shown to be able to directly induce the transcription of CCND1 and FoxM1 via the YAP-TEAD binding site in the FoxM1 promotor region in malignant mesothelioma cells." (PMID 30744076, 2019). "Interestingly, YAP (yes-associated protein) has been shown to be able to directly induce the transcription of CCND1 and FOXM1 via the YAP-TEAD binding site in the FOXM1 promoter in malignant mesothelioma (MM) cells." (PMID 26299613, 2015). "Other than one report in malignant mesothelioma (MM) cells, this is the first evidence that YAP is an important up-stream regulator of FOXM1 in epithelial cancer cells." (PMID 26299613, 2015).
mesothelioma (6 papers, 2012 to 2023). A usually malignant and aggressive neoplasm of the mesothelium which is often associated with exposure to asbestos. "Our results have clearly demonstrated an overexpression of Nrf2, Ref-1, and FOXM1 in mesothelioma towards mesothelium, and a consequent activation of downstream genes controlled by these factors, which in turn regulates antioxidant defense." (PMID 33799965, 2021). "In response to high ROS levels and DNA damage, mesothelioma cells overexpress nuclear factor erythroid 2-related factor 2 (Nrf2), redox effector factor 1 (Ref-1), and forkhead box protein M1 (FOXM1) involved in the antioxidant pathways to reduce oxidative stress." (PMID 37626858, 2023). "Treatment of LP9 cells and a panel of mesothelioma cell lines (e.g. H2373, MO, HP-1 and HM) with 10 μM MG-132 overnight did not extinguish FOXM1 expression (lanes 3–12), whereas MG-132 inhibited expression of FOXM1 in Met5A cells, a mesothelial cell line transformed by SV40 (lanes 1–2)." (PMID 22761781, 2012).
prostate tumor (6 papers, 2014 to 2023). "Critical role of Foxm1 in proliferation of prostate tumor cells was confirmed in orthotopic model using Foxm1-deficient MycCap prostate adenocarcinoma cells." (PMID 25254494, 2014). "Since SPDEF inhibits cell migration, at least in part, through MMP9 and MM13, increased expression of these MMP genes can contribute to Foxm1-mediated rescue of cell migration in SPDEF-deficient prostate tumor cells." (PMID 25254494, 2014). "Altogether, SPDEF inhibits prostate carcinogenesis by preventing Foxm1-regulated proliferation of prostate tumor cells." (PMID 25254494, 2014). "Consistent with findings in the transgenic mice, expression of SPDEF in TRAMP C2 cells decreased Foxm1 mRNA and protein expression in orthotopic prostate tumors." (PMID 25254494, 2014). "In addition, both SETD1A and FOXM1 were found to be overexpressed in mCRPC compared to their expression in primary prostate tumors (GSE35988, GSE32269)." (PMID 32629770, 2020). "Importantly, as revealed by the latest research works, Forkhead box M1 (FoxM1), a gene involved in proliferation, is overexpressed in prostate tumors." (PMID 29313393, 2018). "Compared to the normal tissue, the levels of CENPA, ADCK5, FOXM1, TFAP4, and MAPK were up-regulated in prostate tumor tissue, with a decrease in the expression of LGALS3 and BAG3." (PMID 36891298, 2023). "We analyzed FOXM1 and UHRF1 protein expression levels in 546 prostate tumor tissues using the TCGA data." (PMID 29752436, 2018). "Since SPDEF expression inversely correlated with Foxm1 expression in mouse and human prostate tumors, we examined the possibility that SPDEF directly represses the Foxm1 promoter." (PMID 25254494, 2014). "We found inverse correlations between SPDEF and the Foxm1 oncogene in both mouse and human prostate tumors and demonstrated that SPDEF inhibits tumor cells proliferation through Foxm1 oncogene." (PMID 25254494, 2014).
retinoblastoma (6 papers, 2018 to 2025). A malignant tumor that originates in the nuclear layer of the retina. "Gene Set Enrichment Analysis (GSEA) revealed that these genes were significantly associated with the FOXM1 pathway and retinoblastoma in cancer." (PMID 40313958, 2025). "Functional enrichment analysis highlighted significant associations with FOXM1 signaling pathways and retinoblastoma in cancer." (PMID 40313958, 2025). "Microarray analysis have detected an upregulation of FOXM1 in human retinoblastoma, and in retinoblastoma Y79 cells, FOXM1 depletion has been shown to affect cell invasive capacity by targeting MMP2." (PMID 33953844, 2021). "ABCC4 is transcriptional regulated by FoxM1, promoting carboplatin resistance in retinoblastoma." (PMID 34094932, 2021). "Indeed, MMP2 can be directly regulated by FOXM1 in human retinoblastoma Y-79 cells." (PMID 38338955, 2024). "As FOXM1 is involved in various signaling pathways -other than cell cycle- that control many key cancer properties, it would be interesting to determine whether PL has a effect on these pathways using animal model developping retinoblastoma." (PMID 33953844, 2021). "Treatment of Y-79 human retinoblastoma cell line with CA was able to inhibit the expression levels of MELK and FoxM1 while also reducing the transcriptional activity of FoxM1 to a baseline level." (PMID 36012159, 2022). "We found that FoxM1 protein expression was increased in primary mouse retinoblastoma and PL exposure of WERI-Rb and Y79 induced a decrease in FOXM1 protein content." (PMID 33953844, 2021).
uveal melanoma (6 papers, 2021 to 2025). A melanoma derived from melanocytes of the uveal tract. "For instance, METTL3, an m6A ‘writer’, was downregulated in ocular melanoma tissues, and m6A demethylation of FOXM1 mRNA mediated by ALKBH5 was associated with uveal melanoma (UM) progression." (PMID 36264762, 2022). "Hao and colleagues found that, ALKBH5 mediates m6A demethylation of FOXM1 mRNA and promotes progression of uveal melanoma." (PMID 38098223, 2024). "Thus, FOXM1 contributes to the HGF-mediated protection from senescence in uveal melanoma cells treated with a CDK4/6 inhibitor." (PMID 33806615, 2021). "Hao and colleagues reported that ALKBH5‐mediated m6A demethylation of FOXM1 mRNA promotes malignancies of uveal melanoma, which demonstrated that ALKBH5 increased FOXM1 stability by demethylating FOXM1 mRNA." (PMID 38098223, 2024).
cardiac hypertrophy (5 papers, 2012 to 2025). "Given the vital role Foxm1 plays during cardiac embryogenesis as well as the predisposition for end of life cardiac hypertrophy in αMHC-Cre/Foxm1fl/fl mice, we also investigated the importance of Foxm1 in cardiac pathology using a mouse model of cardiac hypertrophy induced by aortic banding." (PMID 23144938, 2012). "Mice with cardiomyocyte-specific deletion of Foxm1 develop cardiac hypertrophy and fibrosis late in life." (PMID 23144938, 2012). "Thus, Foxm1 expression in cardiomyocytes is critical for age-related cardiac hypertrophy but dispensable for pressure overload-induced cardiomyocyte hypertrophy." (PMID 23144938, 2012). "Given the essential role Foxm1 plays in embryonic cardiac development as well as the propensity for late onset cardiac hypertrophy in mice with cardiomyocyte-specific Foxm1 deletion, we investigated a potential role for Foxm1 in pressure overload-induced cardiac remodeling in young mice." (PMID 23144938, 2012). "Although Foxm1 is known to be involved in tumorigenesis and cardiac development, its role in cardiac hypertrophy remained unknown until now." (PMID 22523601, 2012). "Experiments were performed to examine Foxm1 expression during pathological cardiac hypertrophy." (PMID 23144938, 2012). "A significant reduction in fibrotic markers Fibronectin and Collagen I and cardiac hypertrophy biomarkers ANP and BNP was also observed in the pigs with FOXM1 overexpression after I/R surgery." (PMID 40546121, 2025). "Interference with BRG1 and FOXM1 or the chemical inhibition of FOXM1 can abrogate the cardiac-stress-induced shift from ACE2 to ACE and protect the heart from myocardial hypertrophy." (PMID 37238726, 2023). "BRG1 and FOXM1 were activated to form transcriptional protein complexes at the ACE and ACE2 gene promoters, transcriptionally activating ACE and repressing ACE2, promoting angiotensin II production, and leading to myocardial hypertrophy and fibrosis." (PMID 37238726, 2023). "Brahma-related gene-1 (BRG1) and FOXM1 acted together in pathologically stressed cardiac endothelial cells, triggering the conversion of ACE2 into ACE and angiotensin I into angiotensin II, respectively, leading to myocardial hypertrophy." (PMID 37238726, 2023). "FOXM1 is known to be important for cardiac development, however, there is no report regarding the role of FOXM1 in cardiac hypertrophy." (PMID 22523601, 2012). "Altogether, our results demonstrate that Foxm1 expression in cardiomyocytes is critical for age-induced cardiac hypertrophy but it is not required for TAC-induced hypertrophy." (PMID 23144938, 2012). "Despite a propensity for aging-mediated cardiac hypertrophy when cardiomyocyte-derived Foxm1 is absent, Foxm1 is not a mediator of the timeline or extent of cardiac hypertrophy or remodeling following aortic banding." (PMID 23144938, 2012). "Although Foxm1 protein and message were increased following transaortic constriction, deletion of Foxm1 from cardiomyocytes did not affect survival, the development of cardiac hypertrophy or the degree of cardiac remodeling." (PMID 23144938, 2012). "Foxm1 deletion did not alter mRNA expression of genes critical for cardiac hypertrophy and fibrosis such as α-SMA, collagen 1α1, CaMKIIδ, TNFα, BMP4, MMP9, CXCR4 and Hey2." (PMID 23144938, 2012). "However, Foxm1 deletion did not exacerbate cardiac hypertrophy or fibrosis following chronic pressure overload." (PMID 23144938, 2012). "Thus, Foxm1 expression in cardiomyocytes is not critical for pressure overload-induced cardiac hypertrophy in young mice." (PMID 23144938, 2012).